IL1B (interleukin 1 beta)
Diseases named in the same sentence as IL1B in open-access papers (continued):
Sharing a sentence is not in itself a finding about the gene and the disease.
cystitis (continued). "We identify the cytokine Interleukin-1 beta (IL-1β) as a key immune response determinant in acute cystitis and successfully treat mice with severe acute cystitis by inhibiting IL-1β or the enzyme MMP-7 that processes IL-1β to its active form." (PMID 27732661, 2016). "We identify acute cystitis as an IL-1β-driven, hyper-inflammatory disease, possibly related to other hyper-inflammatory disorders." (PMID 27732661, 2016). "We detected an increase in IL-1β secretion, four hours after infection with acute cystitis (CY) strains CY-17, CY-92, CY-132 or the uropathogenic Escherichia coli strain CFT073 (P < 0.001, compared to uninfected cells, two-tailed unpaired t-test)." (PMID 27732661, 2016). "As IL-1β is processed by the inflammasome, we subsequently examined if mice with intact or defective inflammasome function develop acute cystitis." (PMID 27732661, 2016). "To address if IL-1β activation is a characteristic of acute cystitis strains, we infected human bladder epithelial cells with an epidemiologically defined collection of pediatric acute cystitis isolates (n = 67,)." (PMID 27732661, 2016). "Using IL-1β and MMP-7 as targets for immunotherapy, we succeeded in protecting susceptible Asc-/- mice against acute cystitis, confirming the potential of immunotherapy for this indication." (PMID 27732661, 2016). "The results suggest that the majority of acute cystitis strains activate an IL-1β response in human bladder epithelial cells." (PMID 27732661, 2016). "The severity of acute cystitis was clearly influenced by bacterial virulence as the acute cystitis strains activated IL-1β more efficiently than ABU strains." (PMID 27732661, 2016). "Disease severity was controlled by the mechanism of IL-1β processing and mice with intact inflammasome function developed a moderate, self-limiting form of cystitis." (PMID 27732661, 2016). "Inhibition of caspase 1/11 protected superinfected mice from chronic cystitis, suggesting a role for cytokines downstream of caspase activation including IL-1α and IL-1β, identified in our microarray of four-week bladders." (PMID 25569799, 2015). "In this study we chose chemokines/cytokines IL-1β, IL-6, IL-8, and TNF-α because they are associated with cystitis and systemic inflammation." (PMID 24098552, 2013). "Acute cystitis has been associated with an increase in urine IL-1α, GRO-α, IL-1β, IL-6, IL-8 and TNF-α compared to sterile samples." (PMID 22140570, 2011). "IL-1β has been shown to be elevated in children with cystitis and acute pyelonephritis." (PMID 37228436, 2023). "Also, the mRNA level for IL-1β was elevated in the cystitis and was decreased by SB431542 treatment." (PMID 37931000, 2023). "Taken together, Notch1 signaling may promote microglia activation and production of TNF-α and IL-1β, contributing to mechanical allodynia associated with CYP-induced cystitis." (PMID 34646085, 2021). "Taken together, L-TAMS attenuated mechanical allodynia, depressive-like behavior, and memory deficits in CYP-induced cystitis model rats through prevention of magnesium deficiency and abnormal regulation of TNF-α/NF-κB signaling, IL-1β, and the NR2B subunit in the SDH and hippocampus." (PMID 32241292, 2020). "Besides, the intrathecal injection of exogenous BDNF further decreased the mechanical withdrawal threshold, promoted activation of astrocytes and microglia, and increased the release of TNF-α and IL-1β in the SDH of our CYP-induced cystitis model." (PMID 31931832, 2020). "The results of the western blot analysis indicate that the upregulation of TNF-α, the p-p65/p65 ratio, and IL-1β in the SDH of the cystitis model following L-TAMS treatment was all significantly inhibited on day 20 when compared with the cystitis group without L-TAMS treatment." (PMID 32241292, 2020). "The findings suggest that acute cystitis might resemble hyper-inflammatory disorders, where therapeutic efficacy of IL-1β inhibitors has been documented." (PMID 27732661, 2016).
cystitis (continued). "Finally, we detect elevated levels of these molecules in urine samples from patients with cystitis, suggesting clinical relevance and a potential role of IL-1β and MMP-7 both as therapeutic targets and as biomarkers of infection." (PMID 27732661, 2016). "Moreover, DAPT could inhibit microglia activation and reverse the upregulation of TNF-α and IL-1β in cystitis animals." (PMID 34646085, 2021). "Furthermore, Casp1-/- mice, which have a functional IL-1β deficiency due to defective IL-1β processing and secretion, did not develop acute cystitis." (PMID 27732661, 2016). "The mechanism of IL-1β activation by the acute cystitis strains remains unclear, however." (PMID 27732661, 2016). "We assessed the therapeutic effects of Tt-SOD on HCl-induced cystitis by detecting the serum levels of certain inflammatory factors (TNF-α, IL-1β and IL-6) by specific Elisa kits." (PMID 34783980, 2022). "The establishment of the cystitis model in our present study needs three doses of CYP injections lasting one week, during which proinflammatory cytokines including TNF-α and IL-1β were gradually produced and accumulated." (PMID 34646085, 2021). "We found that the expression of IL-1β and TNF-α were higher in the cystitis group than in the control group." (PMID 31931832, 2020). "Our results provide evidence that BDNF promotes activation of astrocytes and microglia to release TNF-α and IL-1β contributing to aggravating the neuroinflammation and mechanical allodynia through BDNF-TrkB-p38/JNK signaling in CYP-induced cystitis." (PMID 31931832, 2020). "Secreted IL-1β is a strong signature cytokine for NLRP3 inflammasome activation by cytosolic LPS sensing, with a critical role for the development of acute cystitis." (PMID 33102527, 2020). "In our CYP-induced cystitis model, BDNF promoted the activation of astrocytes and microglia to release TNF-α and IL-1β, aggravating neuroinflammation and leading to mechanical allodynia through BDNF-TrkB-p38/JNK signaling." (PMID 31931832, 2020). "Neuroinflammation and synaptic plasticity play an important role in the mechanism of CYP-induced cystitis, and we found that TNF-α/NF-κB signaling and IL-1β were upregulated in both the SDH and hippocampus of the cystitis model." (PMID 32241292, 2020). "Uropathogenic E. coli activate IL-1β through a TLR4-dependent signaling pathway and as a result the acute cystitis phenotype is attenuated in Tlr4−/− and Il1b−/− mice." (PMID 30030504, 2018). "The results confirm the importance of IL-1β and MMP-7 for the pathogenesis of acute cystitis and identify these molecules as functional targets for immunomodulatory therapy." (PMID 27732661, 2016). "To examine the human relevance of the findings in the murine UTI model, we collected urine samples from patients with acute cystitis or ABU and quantified the IL-1β and MMP-7 levels, by ELISA." (PMID 27732661, 2016). "Our results showed that the expression levels of TNF-α, IL-6, and IL-1β were enhanced in E. coli-induced cystitis rat, and knockdown of TPRG1 suppressed the inflammatory response in E. coli-induced cystitis rat through down-regulation of TNF-α, IL-6, and IL-1β." (PMID 34998360, 2022). "Inhibition of Notch1 signaling with a γ-secretase inhibitor, DAPT, could attenuate mechanical allodynia of cystitis animals by suppressing microglia activation as well as overexpression of TNF-α and IL-1β." (PMID 34646085, 2021). "Mice lacking IL-1β, in contrast, are protected from acute cystitis, illustrating the importance of IL-1 for symptoms and pathology." (PMID 34467240, 2021). "Furthermore, treatment with DAPT attenuated mechanical allodynia in CYP-induced cystitis and inhibited microglia activation, leading to decreased production of TNF-α and IL-1β." (PMID 34646085, 2021). "Moreover, TNF-α/NF-κB signaling and pro-inflammatory IL-1β were both upregulated in the SDH and hippocampus of the cystitis rats." (PMID 32241292, 2020).
cystitis (continued). "Furthermore, we explored the co-localization of TNF-α, p-p65 (a principal transcriptional regulator of the activation of the NF-kB pathway), and IL-1β in the SDH and hippocampus of cystitis model rats using double immunofluorescence staining." (PMID 32241292, 2020). "Surprisingly, oral application of L-TAMS could reverse and normalize the expression changes in TNF-α/NF-κB signaling, IL-1β, and NR2B in both the SDH and hippocampus of the CYP-induced cystitis model." (PMID 32241292, 2020). "Finally, elevated levels of IL-1β and MMP-7 were detected in patients with acute cystitis, suggesting a potential role as biomarkers and immunotherapeutic targets." (PMID 27732661, 2016). "Therefore, we performed a western blot analysis and immunofluorescence staining to determine TNF-α/NF-κB signaling as well as IL-1β expression in the SDH and hippocampus of CYP-induced cystitis rats and compared the expression level between groups with and without L-TAMS treatment." (PMID 32241292, 2020). "However, the role of TNF-α/NF-κB signaling and IL-1β expression in the SDH and hippocampus of the CYP-induced cystitis model has not yet been clearly identified." (PMID 32241292, 2020).
keloid (27 papers, 2009 to 2025). An irregularly shaped, elevated mark on the skin caused by deposits of excessive amounts of collagen during wound healing. "Other interleukins, such as IL-1β and IL-10, have also been implicated in keloid pathogenesis through their interactions with the JAK-STAT pathway." (PMID 39201463, 2024). "The expression of TNF‐α, IL‐1β, and IL‐6—key inflammatory cytokines involved in keloid formation—was measured, and the biocompatibility of CNDS@Simvastatin was evaluated to ascertain its impact on important organs." (PMID 39313951, 2025). "IL1β is a well-known pro-inflammatory cytokine that activates inflammatory cells and is upregulated in keloids." (PMID 39558136, 2025). "One study showed a reduced production of PGE2 by IL-1β stimulated keloid fibroblasts compared with those of control fibroblasts." (PMID 39799030, 2025). "IL-1β enhances fibrosis in the late stage of wound healing, and blocking it has been shown to inhibit keloid progression." (PMID 39201463, 2024). "In the context of keloids, the JAK-STAT pathway is activated by pro-inflammatory factors overexpressed in keloid tissues, such as IL-1β, IL-6, IL-17, and tumor necrosis factor (TNF)-α." (PMID 39201463, 2024). "Curcumin has been shown to inhibit the production of inflammation-related cytokines such as tumor necrosis factor-α (TNF-α), interleukin-1β (IL-1β), and interleukin-6 (IL-6), all of which play pivotal roles in keloid formation." (PMID 38284901, 2024). "Mast cell-derived chymase enhances angiotensin II expression, leading to local activation of the renin-angiotensin system and upregulation of TGF-β1, TNF-α, platelet-derived growth factor, and IL-1β in keloid fibroblasts." (PMID 37033989, 2023). "TNF-α-stimulated gene-6 (TSG-6), a protein suppressed in keloid fibroblasts, has been shown to attenuate IL-1β, IL-6, and TNF-α when intradermally injected into hypertrophic scars." (PMID 37033989, 2023). "The reticular dermis has been proposed as the main locale of chronic inflammation underscoring the formation of keloid scars with upregulation of various proinflammatory cytokines, including IL-1α, IL-1β, IL-6, and tumor necrosis factor (TNF)-α." (PMID 37033989, 2023). "The activation of NLRP3 facilitated cleaved caspase-1 processing and promoting the release of IL-1β and IL-18, and increased the inflammatory response in keloid." (PMID 33959031, 2021). "Tranilast inhibited fibroblasts proliferation through lower the production of IL-1β by macrophages and other inflammatory cells, thus lessen keloid." (PMID 33959031, 2021). "Although an increase of IL-1β mRNA was observed in keloid fibroblasts, it was hard to detect IL-1β and IL-18 expression levels in keloid fibroblasts in the present study." (PMID 33126764, 2020). "One report identified up-regulation of the proinflammatory cytokines, IL-1α, IL-1β, IL-6, and TNFα, in keloid fibroblasts." (PMID 33329590, 2020). "Ogawa (2017) suggested that keloids and hypertrophic scars are derived from an abnormal inflammatory reaction in the skin since proinflammatory factors, including IL-1α, IL-1β, IL-6, and TNF-α, are associated with keloid formation." (PMID 33282860, 2020). "IL-1α, IL-1β and TNFα mRNA expression levels decreased in pathologic scars compared to healthy skin, especially IL-1β in keloid scars." (PMID 30765798, 2019). "IL-6, IL-1β, IL-1α, and IL-8 are highly expressed in keloid fibroblasts, and induce the expression of TGFβ1 or render scars more sensitive to external stimuli, thus contributing to the continuous scar expansion and keloid formation." (PMID 38338767, 2024). "In HS and keloid, there is a relatively large number of studies on IL-6, IL-10 and IL-1β." (PMID 33959031, 2021).
keloid (continued). "We determined if NLRP3-mediated inflammation is still activated beyond this time point in keloids by measuring protein levels of cleaved caspase-1 and IL-1β in keloids compared with burn skin (7–10 days after burn, average age 53 years and total body surface area [TBSA] 39%) and normal skin." (PMID 32750036, 2020). "In addition, proinflammatory factors, for example interleukin (IL)-1α, IL-1β, IL-6, and tumor necrosis factor-α are overexpressed in keloid, which proposes that the gene expression of these factors in the skin are responsive to trauma." (PMID 32850775, 2020). "Moreover, proinflammatory factors, such as interleukin (IL)-1α, IL-1β, IL-6, and tumor necrosis factor-α are upregulated in keloid tissues, which suggests that, in patients with keloids, proinflammatory genes in the skin are sensitive to trauma." (PMID 28287424, 2017). "However, FMOD was capable of promoting IL1β expression in keloid- and HS-derived fibroblasts." (PMID 40221432, 2025). "Moreover, keloids feature a persistently inflamed microenvironment, with sustained infiltration of macrophages, mast cells, and T lymphocytes, along with elevated pro‐inflammatory cytokines such as IL‐1β, IL‐6, and TNF‐α." (PMID 41049267, 2025). "However, the expression of cleaved caspase-1, IL-1β and IL-18 was upregulated in human keloids 7–10 days after burn compared with burn and normal skin, suggesting NLRP3-mediated inflammation in keloids and possibly contributing to a persistent inflammatory state." (PMID 38957662, 2024). "Moreover, the use of NLRP3 inhibitor MCC950 reduced the expression of IL-1β, and inhibiting the activation of IL-1 β in inflammatory body may be a method to inhibit keloid." (PMID 33959031, 2021). "However, IL-1β occupied a more important position in keloid and HS." (PMID 33959031, 2021). "NLRP3-dependent IL-1β release may aggravate tissue damage, prolong inflammatory responses, and adversely affect remodeling by inducing continuous myofibroblast differentiation in keloid." (PMID 33126764, 2020). "This is supported by the upregulation of pro-inflammatory cytokines such as interleukin (IL)-1α, IL-1β, IL-6, and tumour necrosis factor (TNF)-α in keloid tissues." (PMID 39119435, 2024). "Here, we confirmed keloid NLRP3 activation (cleaved caspase-1 [P < 0.05], IL-1β [P < 0.05], IL-18 [P < 0.01]) and upregulation in Glut1 (P < 0.001) and glycolytic enzymes." (PMID 32750036, 2020). "mRNA levels of pro-inflammatory cytokines IL-1β and IL-18 activated by the NLRP3 inflammasome were significantly increased in keloid fibroblasts than in normal fibroblasts." (PMID 33126764, 2020). "Immunohistochemical staining showed IL-17, IL-1β, IL-6, and TNF-α level were increased in the perilesional area of keloids compared with normal tissue or the keloid intralesional area." (PMID 31814061, 2020). "Additionally, elevated levels of pro‐inflammatory cytokines such as IL‐1α, IL‐1β, IL‐6, and TNF‐α in keloids contribute to chronic inflammation by increasing fibroblast proliferation, inhibiting apoptosis, and driving ECM synthesis." (PMID 41049267, 2025). "IL-1β stimulates the production of PGE2 by both normal and keloid-derived fibroblasts." (PMID 39799030, 2025). "Inflammatory factors, such as IL-1α, IL-1β, IL-6, and TNF-α, are upregulated in keloid tissues, suggesting that keloids may be considered inflammatory skin disorders, specifically of the reticular dermis, rather than tumors." (PMID 39119435, 2024). "Some of them, such as IL-1β or IL-5, are not detected in keloid patients, and others are present in range between 20 and 40% patients." (PMID 39081787, 2024). "In this study, although not statistically significant, IL-1β induced higher amounts of matrix metalloproteinase-1 (MMP-1) production by cultured skin fibroblasts derived from normal controls than those produced by keloid-derived skin fibroblasts." (PMID 39799030, 2025).
keloid (continued). "With redox balance, TGF-β inhibits the production of pro-inflammatory cytokines such as TNF-α, IL-1β, and IL-6, stimulates IL-10, allows the differentiation of fibroblasts into myofibroblasts to help cover wounds, inhibits the TGF-β/Smad pathway and consequently reduces fibrosis and keloids." (PMID 39061892, 2024). "Moreover, akin to KB-AA35 cells, both IL1β and FMOD induced apoptosis in these abdomen keloid-derived dermal fibroblasts but not the normal skin-derived fibroblasts." (PMID 40221432, 2025). "In addition, our current data offers compelling evidence to suggest that, albeit not activated yet, human keloid- and HS-derived fibroblasts, or at least a subpopulation of these cells, can replicate the targeted apoptosis of BJ- and NHDF-converted myofibroblasts in response to IL1β and FMOD." (PMID 40221432, 2025).